TOR1B (torsin family 1 member B)
Description:
May serve as a molecular chaperone assisting in the proper folding of secreted and/or membrane proteins. Plays a role in non-neural cells nuclear envelope and endoplasmic reticulum integrity. May have a redundant function with TOR1A in non-neural tissues.
Synonyms: DQ1; MGC4386
Tractability: Antibody: UniProt predicts a signal peptide or a membrane-spanning region. PROTAC: its protein half-life has been measured.
Gene: Protein-coding gene on chromosome 9 (129,803,157 to 129,811,281, forward strand). Ensembl gene ENSG00000136816.
Subcellular location: Endoplasmic reticulum lumen; Nucleus membrane
Subcellular location (Human Protein Atlas): Nuclear speckles; Cytosol
Pathways (Reactome):
Vesicle-mediated transport: Cargo recognition for clathrin-mediated endocytosis
Gene Ontology:
Molecular function: ATP hydrolysis activity; identical protein binding; protein binding; kinesin binding; ATP binding
Biological process: endoplasmic reticulum organization; nuclear membrane organization; protein localization to nucleus; response to unfolded protein
Cellular component: endoplasmic reticulum; endoplasmic reticulum lumen; extracellular exosome; nuclear envelope; cytoplasm; endomembrane system; nuclear membrane
Genetic constraint (gnomAD): Loss-of-function variants: 14 observed, 28.5 expected, observed/expected ratio (o/e) 0.49, 90% interval 0.32 to 0.77. The upper end of that interval is the gene's LOEUF score, 0.77, which puts it in group 3 of 6, group 1 being the genes least tolerant of losing a copy. Missense variants: 400 observed, 420.55 expected, observed/expected ratio (o/e) 0.95, 90% interval 0.88 to 1.03. Synonymous variants: 166 observed, 173.12 expected, observed/expected ratio (o/e) 0.96, 90% interval 0.84 to 1.09.
Homologues: Orthologues: chimpanzee TOR1B (99% identical), macaque TOR1B (95% identical), dog TOR1B (90% identical), rat Tor1b (90% identical), mouse Tor1b (88% identical), pig TOR1B (85% identical), guinea pig TOR1B (84% identical), tropical clawed frog tor1b (61% identical), zebrafish tor1 (56% identical), zebrafish tor1l3 (44% identical), zebrafish tor1l1 (44% identical), zebrafish tor1l2 (44% identical), and 4 more. Paralogues in human: TOR1A (66% identical), TOR2A (41% identical), TOR3A (38% identical), TOR4A (22% identical).
Diseases named in the same sentence as TOR1B in open-access papers:
TOR1B is named in the same sentence as 17 diseases in open-access papers, as found by Europe PMC text mining. Sharing a sentence is not in itself a finding about the gene and the disease. The quoted sentences say what the papers report.
breast carcinoma (3 papers, 2023 to 2026). "Elevated expression of TOR1B has been associated with enhanced bone metastasis and poor prognosis in breast cancer patients." (PMID 41596432, 2026). "Recent studies have shed light on the significant relationship between the TOR1B gene and cancer, specifically its role in breast cancer and its association with bone metastasis (BM)." (PMID 38842687, 2024). "This study seeks to explore the prognostic implications of TOR1B across various cancers, with a specific focus on Basal-like Breast Cancer (BLBC) and its underlying cellular mechanisms." (PMID 38842687, 2024). "Further analysis of the relationship between TOR1B expression and OS for the four breast cancer subtypes revealed that high TOR1B expression is a risk factor affecting the OS of patients with Basal-like (HR=3.22, P < 0.05) and Luminal A (HR=2.19, P < 0.05) subtypes." (PMID 38842687, 2024). "Collectively, the data highlight TOR1B as a potential driver of metastasis and cellular stress tolerance in breast cancer, offering a promising target for therapeutic intervention." (PMID 41596432, 2026). "In this study, we focused on the role of TOR1B in breast cancer and further investigated the impact of TOR1B expression on the prognosis of the four PAM50 subtype breast cancers." (PMID 38842687, 2024). "A focal point of our investigation honed in on the prognostic impact of tor1b expression across different subtypes of breast cancer." (PMID 38842687, 2024). "The findings suggest that breast cancer patients exhibiting high tor1b expression are more prone to bone metastasis." (PMID 38842687, 2024). "IHC staining pathological slides from the THPA database revealed that, compared to normal breast tissue, TOR1B protein expression was higher in breast cancer tissues." (PMID 38842687, 2024). "That study delved into the relationship between tor1b expression and the occurrence of bone metastasis events among breast cancer patients, utilizing two public datasets, E-MTAB-365 and GSE2034, for analysis." (PMID 38842687, 2024). "To date, there exists just one study pinpointing tor1b as a predictive factor for bone metastasis in breast cancer patients." (PMID 38842687, 2024). "This upregulation has been validated across different patient datasets, highlighting TOR1B's potential role in the progression of breast cancer to more advanced, metastatic stages." (PMID 38842687, 2024). "The results indicated that TOR1B expression was elevated in all four types of breast cancer compared to normal tissues." (PMID 38842687, 2024). "Research indicates that the expression level of TOR1B is significantly upregulated in breast cancer (BC) patients who develop bone metastasis." (PMID 38842687, 2024). "Evidence suggests that HIF1A may regulate TOR1B expression in basal-like breast cancer cells, linking TOR1B to hypoxia-related signaling pathways." (PMID 41596432, 2026). "Therefore, investigating the role and mechanisms of TOR1B in the progression of malignant tumors, particularly in breast cancer, can offer new insights for developing novel targeted therapies for malignant tumors." (PMID 38842687, 2024). "The interaction between TOR1B and metabolic pathways, as well as its regulation by HIF-1α, suggests its significance in adapting to hypoxia, thereby positioning TOR1B as a promising therapeutic target for aggressive breast cancer subtypes." (PMID 38842687, 2024).
autoimmune pancreatitis (1 paper, 2022). "The antigens TOR1B and GPR173 had already been described as markers for discriminating PDAC from chronic and autoimmune pancreatitis." (PMID 35892825, 2022).
depression (1 paper, 2012). "The 15 target genes include DYNLT1, GCH1, TOR1B, DISC1, MEF2A and ST3GAL5 that to date were never related to an IFN-α regulation while all of them have been described in association with brain development or depression." (PMID 22701688, 2012).
prostate carcinoma (1 paper, 2023). A carcinoma that arises from epithelial cells of the prostate gland. "This study found that prostate cancer patients with high expression of TOR1B had a poor prognosis after radiotherapy." (PMID 37726767, 2023). "This indicates that patients with prostate cancer with high expression of TOR1B are not suitable for radiotherapy." (PMID 37726767, 2023).
recurrent major depression (1 paper, 2012). "TOR1B, which shows immunoreactivity in all subfields of the hippocampus, is homologue to TOR1A (alternative name: DYT1), is associated with early-onset recurrent major depression and is involved in the regulation of dopamine release." (PMID 22701688, 2012).
Torsion dystonia (1 paper, 2017). Sustained involuntary muscle contractions that produce twisting and repetitive movements of the body. "For example, polymorphisms in the TOR1A/TOR1B region are associated with torsion dystonia, a neurological disorder characterized by debilitating muscle contractions." (PMID 27755386, 2017).
cancer (3 papers, 2023 to 2024). A tumor composed of atypical neoplastic, often pleomorphic cells that invade other tissues. "The importance of TOR1B in maintaining the ER's integrity is critical for cellular health, as disruptions in ER function can lead to stress responses that are implicated in numerous diseases, including neurodegenerative disorders and cancer." (PMID 38842687, 2024). "In vitro experiments further revealed that TOR1B knockdown augmented apoptosis and influenced metabolic activity, particularly under hypoxic conditions, highlighting its potential role in cancer cell adaptation to stress." (PMID 38842687, 2024). "Our research revealed that TOR1B plays a critical role in cancer progression, particularly in BLBC, where its aberrant expression correlates with poor prognosis." (PMID 38842687, 2024). "In this study, we embarked on a pan-cancer analysis of tor1b expression and its prognostic implications across various malignancies, drawing upon data from TCGA and GEO databases." (PMID 38842687, 2024). "We discovered that TOR1B is aberrantly expressed in various malignant tumors, and the expression levels of TOR1B in these malignant tumor tissues are associated with patient prognosis." (PMID 38842687, 2024). "In recent years, studies have found that TOR1B plays an important role in the development of malignant tumours." (PMID 37726767, 2023). "In this study, we conducted a pan-cancer analysis of TOR1B for the first time." (PMID 38842687, 2024). "In cancer cells, we found high expression levels of TOR1B in the nucleus and endoplasmic reticulum." (PMID 36707670, 2023). "The pan-cancer differential expression analysis of TOR1B, conducted with combined data from the TCGA, TARGET, and GTEx databases, indicates that TOR1B is differentially expressed in 26 types of cancer." (PMID 38842687, 2024). "Our findings indicate that TOR1B is overexpressed in BLBC and other cancers, consistently correlating with poorer prognosis." (PMID 38842687, 2024). "By analyzing TOR1B's interaction with metabolic pathways and its regulation by HIF-1α, we identified it as a key player in cancer cell adaptation to hypoxia." (PMID 38842687, 2024). "Overall, our study underscores the importance of TOR1B in cancer progression, particularly in BLBC, where it serves as a notable prognostic indicator." (PMID 38842687, 2024). "We combined the expression data of TOR1B and follow-up information from 44 types of tumors in the TCGA and TARGET databases to analyze the relationship between TOR1B expression and the OS rate in these cancers." (PMID 38842687, 2024).
tumor (3 papers, 2022 to 2024). "HIF1A, one of the most critical genes affecting tumor cell hypoxia tolerance, showed a positive correlation with TOR1B expression in BLBC samples from the TCGA database (ρ=0.4, p < 0.01), indicating co-expression between the two." (PMID 38842687, 2024). "In the realm of tumor research, investigations into the correlation involving tor1b remain notably sparse." (PMID 38842687, 2024). "Following normalization of both tumor and normal tissue samples, differential expression analysis of TOR1B was performed." (PMID 38842687, 2024). "These outcomes were consistent with prior results obtained using the TCGA database, which had identified aberrant expression of TOR1B in BCLC tumor tissues." (PMID 38842687, 2024). "The integration of TOR1B expression data from tumor and normal tissues across three GEO datasets for differential expression analysis revealed that TOR1B was aberrantly highly expressed in BCLC tumor tissues." (PMID 38842687, 2024). "Prognostic indicators that may affect DFS include TOR1B expression levels (P < 0.05, HR = 6.028), tumor size (P < 0.05, HR = 7.366), and metastasis (P < 0.05, HR = 16.942)." (PMID 38842687, 2024). "Prognostic indicators that may affect DFS include TOR1B expression levels (P < 0.05, HR = 4.305), tumor size (P < 0.05, HR = 3.89), and metastasis (P < 0.05, HR = 22.417)." (PMID 38842687, 2024). "In the multivariate analysis, prognostic indicators that may affect OS include TOR1B expression levels (P < 0.05, HR = 4.83) and tumor size (P < 0.05, HR = 6.178)." (PMID 38842687, 2024). "We hypothesized that high TOR1B expression, by reducing reliance on the normal aerobic energy pathway, may enhance the hypoxia tolerance of BCLC tumor cells, potentially preventing cell death due to energy deficiency." (PMID 38842687, 2024). "The results showed that the age and tumor grade of BC patients were not significantly correlated with TOR1B expression (p > 0.05)." (PMID 36707670, 2023). "We first examined genes that may render cell-growth advantage through analysis of our CRISPR/Cas9 perturbation screen in JeKo-1 cells and found that many critical tumor suppressors were located on chr9, including CDKN2A, SMARCA2, FBXO10, and TOR1B (z score ≥ 1)." (PMID 34882582, 2022).
TOR1B also shares sentences with these, for which no sentence is quoted: Obesity (2 papers); acute myeloid leukemia (1); Adrenocortical Carcinoma (1); Breast Invasive Carcinoma (1); Cirrhosis (1); glioblastoma (1); glioma (1); lung squamous cell carcinoma (1); neurological disorder (1).